CXCL11 (C-X-C motif chemokine ligand 11)
Diseases named in the same sentence as CXCL11 in open-access papers (continued):
Sharing a sentence is not in itself a finding about the gene and the disease.
melanoma (continued). "Indeed, systemic administration of IFNγ increased levels of CXCL10 and intratumoral T cell infiltration in a phase 0 clinical trial for sarcoma, and intratumoral injection of IFNγ increased tumor CXCL10 and CXCL11 in melanoma patients." (PMID 33603130, 2022). "Higher levels of CXCL9, CXCL10, and CXCL11 were also detected in melanoma patients’ tumors following treatment with ipilimumab, an antagonistic antibody against cytotoxic T-lymphocyte-associated protein 4 (CTLA4), another inhibitory receptor expressed by T cells." (PMID 33603130, 2022). "Because the 4 genes IGHV1-18, CXCL11, LTF and HLA-DQB1 are associated with tumor immunity, we used the TIMER database to analyze the correlation between the prognosis of these 4 genes and the infiltration of immune cell subtypes in melanoma." (PMID 33585219, 2020). "CXCL11 has been found uniquely expressed in the melanoma with rich lymphocyte, and may play a potential role in the construction of tumor microenvironment by recruiting activated T-cells." (PMID 33585219, 2020). "At least two-fold upregulation of CXCL9, CXCL10, and CXCL11 was observed in all cancer types including melanoma (n = 77), breast cancer (n = 40), brain cancer (n = 198), and lung cancer when comparing samples with high to low MOTIscores, with significance for melanoma and breast cancer." (PMID 41463470, 2025). "Treatment with the anti-tumor drug Decarbazine (DTIC) reduced melanoma cell migration by decreasing protein concentrations of the migrating chemokines CXCL2 and CXCL11." (PMID 40429702, 2025). "Five hub genes including CXCL11, ICAM1, LEF1, MITF, and STAT1 were identified, SUZ12, SOX2, TCF3, NANOG, and SMAD4 were determined as the most significant TFs in metastatic-melanoma." (PMID 39820173, 2025). "Survival analysis also disclosed that the differential expression of CXCL11, ICAM1, and STAT1 was accompanying through poor prognosis in progressive melanoma." (PMID 39820173, 2025). "Additionally, the presence of inflammatory (CXCL-11) and lymphoid (CXCL-13) chemokines has been associated with the recruitment of tumor infiltrating lymphocytes, namely CD4+ T cells, CD8+ T cells and mature dendritic cells, to promote melanoma cell destruction." (PMID 38812776, 2024). "Upregulations of Cxcl9, Cxcl10, Cxcl11, Ccl5, Tap1, CD74, Irf1, Icam1, CD40, Fas and PD-L1 were detected after Mi-2β silencing and the anti-PD-1 treatment in BRafV600E/Ptennull melanomas." (PMID 38461299, 2024). "For other chemokines, most of them tended to express higher in FGFR Mut melanoma, such as CCL5, CCL19, CXCL9, CXCL10, CXCL11, CXCL13 and CXCL14 (all P > 0.05)." (PMID 36426352, 2022). "Taken together, melanoma cells secreted a variety of proinflammatory factors, mainly cytokines, such as IL-1β and IL-8, and chemokines, such as CXCL10, CXCL11, and CCL20, during CIS, while during TIS, melanoma cells produced lower levels of SASP proteins." (PMID 35563820, 2022). "Similar findings have been reported for cisplatin and DTX, which promoted lymphocyte recruitment and infiltration within tumor by inducing melanoma cells to express CXCL10 and CXCL11, respectively." (PMID 34712615, 2021). "In a mouse model of spontaneous melanoma, both DTIC and TMZ have been shown to induce the secretion of chemokines such as CCL5, CXCL9, CXCL10 and CXCL11 by melanoma cells." (PMID 34712615, 2021). "One of them, the C-X-C motif chemokine ligand 11 (CXCL11), is able to reverse melanoma cells motility, when upregulated in BANCR-depleted cells." (PMID 34638331, 2021). "In another report, intratumoral injection of IFN-b also increased CD8+ TILs in melanoma by the induction of M1 macrophage-related chemokines (CXCL9, CXCL10, CXCL11), leading to enhancement of the anti-tumor effects of anti-PD1 Abs for melanoma in vivo." (PMID 32707850, 2020).
melanoma (continued). "It has been indicated in a mouse model of melanoma that T cell infiltration is enhanced by 18-fold in melanoma cells through inhibition of VEGF and consequently overexpression of CXCL10 and CXCL11 in tumor vessels." (PMID 32499786, 2020). "Previously, we found that melanoma-activated TIL induced MSCs to produce a wide variety of chemokines including the Th1 chemokines CCL5, CXCL9, CXCL10 and CXCL11 and the Th1 cytokine IL-125." (PMID 27211104, 2016). "Most chemokines were expressed intracellularly in all melanoma cell lines (CXCL9, CXCL11, CXCL12, CCL19, CCL21 and CCL27)." (PMID 24559071, 2014). "CXCR3 expression in human and murine melanoma cell lines has been suggested by others to mediate directional cell migration along the chemokine gradients of CXCL9, CXCL10 and CXCL11." (PMID 21179030, 2011). "In the melanoma sample (patient 16), CXCL9, CXCL10, CXCL11, and CXCL13 as well as tumor growth factor beta (TGF-β) were higher at the tumor periphery, indicating that T cells in this region are subject to a unique chemokine and cytokine milieu compared with those deeper within the tumor." (PMID 35584630, 2022). "mEHT induced the upregulation of the chemoattractant CXCL11 and increased the expression of the matrix metalloproteinase MMP2 which could account for the NK-cell attraction into the treated melanoma." (PMID 33732640, 2021). "Compared with the normal melanocytes, IGHV1-18, CXCL11 and HLA-DQB1 were highly expressed in melanoma cell line A375, A815 and SK-MEL-28, and LTF was downregulated in melanoma cell line A375, A815 and SK-MEL-28, and both had statistical significance (P < 0.05)." (PMID 33585219, 2020). "In this study, we focused on the immune infiltrating status in melanoma and selected IGHV1-18, CXCL11, LTF and HLA-DQB1 from immune cell infiltration cluster as immune cell infiltration-related DEGs through the analysis of differences in melanoma samples and the construction of prognostic models." (PMID 33585219, 2020). "They demonstrated that inhibition of tumor acidosis by adenylyl cyclase inhibitor MDL-12 induces NOS, CXCL9, CXCL11 and TNF-α-expressing proinflammatory TAMs that phenotypically resemble classical M1 macrophages, leading to suppression of tumor growth in B16 mouse melanoma." (PMID 32707850, 2020). "Indeed, it has been shown that mouse melanoma B16F10 cells constitutively express CXCR3, and its ligands CXCL9/Mig, CXCL10/IP-10, and CXCL11/I-TAC induce cellular responses in vitro, such as actin polymerization, migration, invasion, and cell survival." (PMID 24559071, 2014). "Lipopolysaccharides can stimulate normal human melanocytes to produce IL-1β, TNFα, IL-6, IL-8, CCL2, CCl3, and CCL5, and chemotherapy of melanoma-bearing mice results in enhanced expression of CCL5 and the CXCR3 ligands CXCL9, CXCL10, and CXCl11 by tumor cells." (PMID 22745913, 2012). "The CXCL9, CXCL10, and CXCL11/CXCR3 axis was generally considered to have antiangiogenic effects on endothelial cells and has been reported as effective tumor angiogenesis inhibitors in some in vivo tumor models, including pancreatic cancer, breast cancer, lung cancer, and melanoma." (PMID 32685487, 2020). "Although the chemokines CXCL9, CXCL10 and CXCL11 were reported to have an angiostatic effect when expressed by melanoma cells, our study suggests that the chemokine CXCL9 may promote additional metastasis, when it is expressed in TuECs, by means of increasing transendothelial and melanoma migration." (PMID 21179030, 2011). "The role in melanoma of the recently discovered CXCR7, which binds to CXCL11 and CXCL12 is still not clear." (PMID 24559071, 2014).
breast carcinoma (43 papers, 2012 to 2026). "CXCL9, CXCL10, and CXCL11 have tumor-promoting abilities and have been associated with advanced human cancer, particularly in elderly breast cancer patients' progression and metastasis." (PMID 40584290, 2025). "LRPPRC aggravates inflammation to promote malignancy of breast cancer cell through increasing the m6A modification of C-X-C motif chemokine ligand 11 (CXCL11)." (PMID 40555877, 2025). "CXCL11 levels were higher in conditioned media from HR+ breast cancer cells cocultured with CD8+ T cells." (PMID 41364532, 2025). "Proteins involved in chemotaxis and inflammation, including CCL3, CCL4, CXCL11, and CCL23, were only found to be associated with long-term breast cancer risk after five years, suggesting the long-term effect of inflammation on breast cancer risk." (PMID 40665092, 2025). "A recent study has reported that senescent epithelial cells induced by therapy can secrete SASP factors, which facilitate the invasion of breast cancer cells via the CXCL11/CXCR3/Ak strain transforming (AKT)/extracellular signal-regulated kinase (ERK) pathway." (PMID 40584290, 2025). "Their investigation revealed a notable downregulation in the expression level of RAMP2-AS1 in both breast cancer tissues and cells, while CXCL11 exhibited significantly elevated expression levels." (PMID 37705098, 2023). "CXCL11 increases the frequency of tumor-infiltrating lymphocytes and inhibits tumor growth in both breast cancer and T-cell lymphoma." (PMID 37547756, 2023). "In conclusion, RAMP2-AS1 exerts a suppressive effect on the malignant characteristics of breast cancer through the inhibition of CXCL11, mediated by DNMT1 and DNMT3B." (PMID 37705098, 2023). "Studies have shown that induction of CXCL10 and CXCL11 expression in breast cancer cells enhances the infiltration of CD8 T cells." (PMID 37388244, 2023). "CXCL11 expression promoted the migration and invasion of human breast cancer cells and was positively correlated with the overall survival of lung cancer patients." (PMID 36290882, 2022). "CXCL11 can enhance antitumor immune cell migration and infiltration in the breast cancer tissue." (PMID 38217262, 2024). "Elevated CXCL11 also increases the aggressiveness of breast cancer cells." (PMID 38609887, 2024). "Interestingly, LCMR1 (MED19) reportedly down-regulates C-X-C motif chemokine ligand 11 (CXCL11) in breast cancer; blocking LCMR1 contributes to high CXCL11 levels and positively correlates with antitumor immune responses." (PMID 38001705, 2023). "There were 12 unique analyses with significantly high expression of CXCL11 in breast cancer and 12 unique analyses in colon cancer, and 16 unique analyses with significantly low expression of CXCL12 in breast cancer, and 3 unique analyses with significantly low expression in pancreatic cancer." (PMID 34439306, 2021). "AMG487 inhibits CXCR3 signaling by obstructing binding of CXCR3 ligands and has been shown to inhibit in vitro CXCR3-mediated cell migration by the CXCR3 chemokines, CXCL9, CXCL10, and CXCL11, and to inhibit lung metastasis in a mouse model of metastatic breast cancer." (PMID 25798946, 2015). "The IHC score results demonstrated that ADAMTS12, AEBP1, CXCL11, and EPPK1 protein levels were higher in breast cancer samples than in normal controls." (PMID 35505821, 2022). "Several differentially expressed mRNAs in HER2-positive breast cancer (including CXCL2, CXCL12, CXCL10, CXCL11, CXCL9 and CXCL14) were enriched in the biology processes of chemokine receptor binding and chemokine activity." (PMID 34257572, 2021). "The results indicated that the expression levels of CXCL9, CXCL10, CXCL11, and CXCL13 were marked higher in breast cancer tissues than in normal tissues, while the expression levels of CXCL1, CXCL2, CXCL3, and CXCL12 were lower inversely." (PMID 32963527, 2020).
breast carcinoma (continued). "Among the inversely correlated genes were four chemokines, CCL5, CXCL9, CXCL10 and CXCL11 indicating that IRX2 might be actively involved in the regulation of chemokine secretion by mediating the transcriptional repression of these chemokines in breast cancer cells." (PMID 26560478, 2015). "The association of hepatocyte growth factor (HGF) with breast cancer was stronger in Estrogen Receptor (ER)-negative patients, while CASP8, CXCL11, MMP7, and C–C motif chemokine 4 (CCL4) were associated with ER-positive breast cancer." (PMID 40665092, 2025). "In breast cancer it is confirmed CIS could change TME and increase the aggressiveness through the CXCL11 signaling pathway." (PMID 38370348, 2023). "A similar prediction could be made using five genes most differentially expressed in the breast cancer stroma, PSPHL, CXCL10, CXCL11, ISG20, and GMDS." (PMID 32714862, 2020). "Interestingly, CXCL10, CXCL11, and ISG20 are IFN-γ-regulated genes, which is consistent with the presence of interferon signature found in breast cancer from AA patients." (PMID 32714862, 2020). "Besides, HECTD3, PSMB10, UBD, UBE2C, and UBE2S involved in the ubiquitin proteasome pathway, as well as CCL2, CCR1, CXCL10, CXCL11, and IL2RG implicated in the cytokine–cytokine receptor interaction pathway, might be used for evaluating the efficacy of neoadjuvant chemotherapy in breast cancer." (PMID 29685151, 2018). "This is in agreement with clinical studies in human breast cancer identifying CXCL9, rather than CXCL10 or CXCL11, as a potential biomarker for diagnosis of breast cancer and therapy response, suggestive of its protective role in breast cancer biology." (PMID 22333315, 2012). "Notably, the proportion of CXCL11+ TAMs did not vary significantly across different molecular subtypes and stages of breast cancer, possibly due to its dual role in tumor immunity." (PMID 39232806, 2024). "Notably, four hub genes (SAA1, CCR3, CCR5 and CXCL11) were unique among the breast cancer LM2 cell line; they were not identified among DEGs from the metastatic BrM2 cell line." (PMID 35045088, 2022). "Therefore, CCL2, CCR1, CXCL10, CXCL11, and IL2RG might be involved in neoadjuvant chemotherapy in breast cancer via the cytokine–cytokine receptor interaction pathway." (PMID 29685151, 2018). "For interaction studies, we chose MCF-7 breast cancer cells, since they highly express CXCR4 and CXCR7 at the protein level but not CXCR3 (another target for CXCL11)." (PMID 24770893, 2014). "This suggests a primary role of the CXCR7/CXCL11 chemokine axis in the response of OC cells to estrogen, bringing selectivity in targeting the CXCR7 axis compared to other ER‐positive gynecologic cancer cells, such as breast cancer cells which did not exhibit CXCR7 upregulation by estrogen." (PMID 30051594, 2018).
viral infections (40 papers, 2007 to 2026). "First, we observed that genes that were upregulated in mock-infection vs. input were frequently downregulated in both wild-type and Δvxcl1 virus infections, such as cytokine-encoding Cxcl11, or Fdft1 and Fdps, which are both coding for enzymes in the cholesterol synthesis pathway." (PMID 38077365, 2023). "While CXCR3 is strongly associated with the CXCL11 chemokine, CXCL11 recruits innate natural killer cells, is involved in protective immunity by affecting the adaptive immune reaction toward tumors and viral infections, and attracts T-effector cells." (PMID 34438623, 2021). "Moreover, the Tryptophanyl-tRNA Synthetase encoding WARS1, which stimulates immunity against viral infection, chemokines CXCL11, CCL4 and CCL4 receptor CCR5 were also significantly downregulated in low viral load positive old samples compared to age matched control." (PMID 32511341, 2020). "Activation of the IFN-I response by LGTV and ZIKV infections was also supported by significant increases in the CXCL10 and CXCL11 expression after virus infection." (PMID 40431659, 2025). "Several of the upregulated genes indicated a cellular response to viral infection (CXCL11, CCL8, DEFB103A, IFI6, ACOD1, and DEFB4A)." (PMID 38755665, 2024). "CXCR3 and its ligands CXCL9, CXCL10 and CXCL11 are known to regulate leukocyte recruitment during numerous viral infections." (PMID 39803542, 2024). "We also examined the expression of CXCL11, a chemokine and airway epithelial cell biomarker of viral infections." (PMID 36992456, 2023). "Recent evidence points toward non-redundant roles for three IFN-induced CXCR3 ligands in vivo, for example, CXCL10 during viral infections and CXCL11 during allergic reactions." (PMID 30473680, 2018). "Additionally, CXCL10 and CXCL11 were pinpointed, shedding light on the organ tissue equivalent’s innate immune response to viral infections." (PMID 38957806, 2024). "CXCL11 expression during viral infection was generally static in both cell types assayed." (PMID 35085371, 2022). "Although the actual role of CXCL11 in viral infections remains unclear, the peak level of CXCL11 mRNA coincides with the peak of viremia and the CXCL11 protein was reported to inhibit viral growth." (PMID 25550087, 2015). "These differential responses (including transcripts encoding CCL1, CCL6, CXCL11, and CXCL12) not only vary minimally with age at inoculation, the differential responses themselves are minimal, demonstrating at most 2-fold induction in response to virus infection." (PMID 21078159, 2010). "In viral infections, inhibiting the expression of miR-369-3p dramatically reduces the expression of antiviral response genes, including CCL3, CCL5, CTSS, CXCL11, and IRF3." (PMID 37509488, 2023). "Here, we show that CXCL10, CXCL11 and CCL5 known to be expressed in the CNS during various viral infections including those by encephalitic arboviruses were upregulated by either virus, pointing to the induction of a strong inflammatory response." (PMID 33799906, 2021). "TNFAIP3, ULBP1 and TIAM1 were consistently down-regulated by viral infection, while CCL8, CCL11, CXCL11, NCF2, CSF3 and PRKCB were significantly up-regulated after infection." (PMID 28938587, 2017). "In asthmatics IFN-γ, CXCL10/IP10, CXCL11/ITAC, IL-15 and IL-5 increased in bronchial lining fluid following viral infection (all P < 0.05)." (PMID 28373098, 2017). "However, in the serum of SARS-CoV-2–infected macaques, we found a transient virus infection–related increase in 2 interferon-γ–driven inflammatory cytokines, CXCL10 and CXCL11, and an increase of CCL2, whereas interleukin-6 was elevated in only 1 animal." (PMID 40876955, 2026). "Additionally, PDCoV infection increased the transcription of the chemokines CCL2, CCL4, CXCL9, CXCL10 and CXCL11, suggesting that these chemokines may contribute to the recruitment and regulation of macrophages or other inflammatory cells to the sites of virus infection." (PMID 35328701, 2022).
viral infections (continued). "Using quantitative PCR (qPCR) for common respiratory viruses and for two genes known to be highly upregulated in viral infections (CCL8/CXCL11), we screened 92 asthmatic and 69 healthy children without illness for respiratory virus infections." (PMID 28103897, 2017). "Our results demonstrate that genes related to important immune pathways such as antigen presentation, inflammation, apoptosis and response to virus (Cxcl10, CxCl11, Ccl5, Ifr7, Ifi27 Oas1b, Fcerg1,Mif, Clusterin and MHC class II) were upregulated as a result of virus infection." (PMID 18558011, 2008). "Inflammatory gene sets, and individual inflammatory maker genes CXCL10, CXCL11 and CCL5, were significantly increased in the buffer-only treated cultures from 24 hours to 48 hours, in a viral dose-dependent manner, indicating that the virus infection drives this expression over time." (PMID 39621805, 2024). "In particular, fatal disease was characterized by upregulated levels of IP9/CXCL11 and IP10/CXCL10, which are also expressed by microvascular endothelial cells upon activation or infection with dengue virus, suggesting a general rather than SARS-CoV-2-specific response to viral infection." (PMID 35141292, 2021).